FBXW7 (F-box and WD repeat domain containing 7)
Diseases named in the same sentence as FBXW7 in open-access papers (continued):
Sharing a sentence is not in itself a finding about the gene and the disease.
cervical carcinoma (38 papers, 2015 to 2025). A carcinoma arising from either the exocervical squamous epithelium or the endocervical glandular epithelium. "In cervical cancer cells, an up-regulation of miR-92a causes a down-regulation of FBXW7, thereby stimulating tumor cell proliferation and invasion." (PMID 37047300, 2023). "In our study, the PIK3CA, KMT2C, KMT2D, LRP1B, and FBXW7 genes were the five genes with the highest mutation frequencies in cervical cancer samples, which is mostly consistent with the results in TCGA." (PMID 36333792, 2022). "In our cervical cancer data, the mutated genes involved in this pathway included FBXW7 (altered in 17%), HUWE1 (altered in 13%), and BIRC6 (altered in 9%)." (PMID 27998038, 2017). "FBXW7 is a gene recently described as mutated in cervical carcinoma 33 with two missense mutations already described, R505G and R456C." (PMID 26155992, 2015). "Most PTEN and FBXW7 cervical carcinoma mutations are considered likely oncogenic in OncoKB database, while for a few the significance is unknown." (PMID 33435133, 2021). "Similarly, in cervical cancer cells upregulation of miR-92a caused downregulation FBXW7, thereby promoting cell proliferation and invasion." (PMID 30791487, 2019). "Mutations in FBXW7 which encodes a protein involved in ubiquination and proteasome degradation of oncoproteins as well as DNA double strand break response, are frequently present in cervical cancers and loss of function has been correlated with chemotherapy resistance and poor clinical outcomes." (PMID 36201462, 2022). "The landmark studies by the Cancer Genome Atlas (TCGA) have reported that the most frequent mutations in cervical cancer are PIK3CA (26%), EP300 (11%), FBXW7 (11%), and PTEN (8%)." (PMID 37256181, 2023). "Tian et al30 identified that the cervical cancer patients with five notable nonsynonymous mutant genes (PIK3CA, BRAF, GNA11, FBXW7, and CDH1) metastatic relapse significantly mutated mutations had significantly poor DFS and OS." (PMID 35762423, 2023). "Conversely, LINC00173 is reported to be downregulated in cervical cancer, and it inhibits cell proliferation and invasion by regulating the miR‐182‐5p/FBXW7 axis." (PMID 36606322, 2023). "In conclusion, our findings demonstrated that miR-103a-3p functions an oncogenic role in cervical cancer by inhibiting FBXW7 function." (PMID 35094292, 2022). "In our current study, FBXW7 was validated as a direct and functional target of miR-103a-3p in cervical cancer." (PMID 35094292, 2022). "The most frequent significantly mutated genes (SMGs) across the 430 cervical carcinomas were previously reported and included PIK3CA (27%), KMT2C (also known as MLL3) (19%), KMT2D (also known as MLL2) (13%), EP300 (12%), FBXW7 (12%), FAT1 (8%), and PTEN (8%)." (PMID 34620846, 2021). "miR-92a-5p is thought to induce its effects by targeting essential molecules in the cell cycle, including Retinoblastoma (RB), Dickkopfrelated protein 3 (DKK3) and FBXW7 mRNA and then, promotes cell proliferation and invasion in cervical cancer." (PMID 33906322, 2021). "Accumulating studies have identified various genomic mutations of PIK3CA, EP300, FBXW7, PTEN, HLA-A, ARID1A and so on in different cervical cancer tissues." (PMID 32123519, 2020). "Rather, monoallelic and biallelic FBXW7 gene deletions or promoter hypermethylation are predominantly observed in different cancers for example bladder, breast and cervical cancer." (PMID 30791487, 2019).
cervical carcinoma (continued). "Overexpression of miR-92a targeting FBXW7 in cervical cancer cells and increased proliferation and tumorgenesis." (PMID 29911120, 2018). "miR-92a-3p promotes cell proliferation and cell cycle progression via inhibiting p21 or FBXW7 in cervical cancer." (PMID 29552296, 2018). "MiR‐92a also induces cell proliferation and invasion by targeting F‐box and WD repeat domain‐containing 7 (FBXW7) in cervical cancer." (PMID 29266846, 2018). "These pathways and the recurrently mutated genes involved therein, such as EP300, ARID1A, FBXW7, NFE2L2, PIK3CA, and ERBB2, were all found to be pathogenic in previous cervical cancer studies." (PMID 28390392, 2017). "Another study on cervical cancer cases of European origin identified PIK3CA, KRAS and FBXW7 to be the most mutated." (PMID 27829003, 2016). "Moreover, previous studies on the genomic landscape of cervical cancer have identified frequent alterations in genes, such as PIK3CA, EP300, FBXW7, and APOBEC signatures, associated with the process of carcinogenesis of virus-associated diseases." (PMID 37256181, 2023). "Moreover, miR-92a overexpression induced the proliferation and invasion of cervical cancer cells by targeting F-Box and WD Repeat Domain Containing 7 (Zhou., 2015).This investigation suggesting that miR-92a plays a role as a carcinogenic miRNA in ALL." (PMID 34048187, 2021). "miR-92a-3p targeted FBXW7 to promote cell proliferation and invasion in cervical cancer." (PMID 32140077, 2020). "Moreover, Yu and colleagues reported that overexpression of miR-92a promoted the proliferation and invasion of cervical cancer cells by targeting FBXW7." (PMID 30926679, 2019). "Furthermore, EP300, ARID1A, FBXW7, NFE2L2, PIK3CA, and ERBB2 have all been previously reported as pathogenic genes in cervical cancer, and we highlighted the roles of MLL2, MLL3, and CREBBP in the tumorigenesis." (PMID 28390392, 2017). "Additionally, FBXW7 and EP300 mutations have already been reported in cervical cancer." (PMID 35205332, 2022). "FBXW7 is a tumor suppressor strongly suppressed the cancer cells proliferation, however the role of FBXW7 can be significantly inhibited by several mi-RNAs including miR-25, miR-92, miR-182, miR194, miR-223 and miR-503 in gastric, esophageal, colorectal, breast and cervical cancer cells 175-179." (PMID 32226545, 2020). "The expression of miR-92a is significantly upregulated in cervical cancer (CC) tissues and cell lines, it inhibits the expression level of FBXW7 by directly binding to the 3’-UTR of FBXW7 mRNA." (PMID 36998461, 2023). "For example, PIK3CA was an inclusion criterion in one clinical trial (NCT02957266) for directing cervical carcinoma therapy, as well as, ERBB3 and FBXW7 were considered as biomarkers in several clinical trials for malignant solid tumor." (PMID 34221990, 2021). "When HeLa cervical cancer cells were treated with MAPK pathway inhibitor UO-126, FBXW7 expression was remarkably increased, indicating the involvement of FBXW7 in suppressing HeLa cell proliferation." (PMID 30791487, 2019). "In cervical cancer, there is a marked upregulation of microRNA miR-92a, which binds to 3’UTR of the FBXW7 and inhibits the expression of FBXW7, thus promoting tumor progression and invasion." (PMID 30791487, 2019).
cervical carcinoma (continued). "There is evidence indicating that the lncRNA FENDRR/miR-15b-5p/TUBA1A axis suppresses cervical cancer cell proliferation and invasion 48, and the lncRNA TTN-AS1 suppresses ovarian cancer cell proliferation and invasion by targeting miR-15b-5p and regulating FBXW7 expression." (PMID 38911389, 2024).
melanoma (37 papers, 2014 to 2025). A malignant, usually aggressive tumor composed of atypical, neoplastic melanocytes. "A low level of FBXW7 expression is associated with increased melanoma cell migration, metastatic potential and increased levels of genes promoting tumour angiogenesis." (PMID 39340537, 2024). "Existing evidence has shown that FBXW7α is a well-known ubiquitinating enemy of HSF1, and FBXW7 deficiency promotes HSF1 accumulation in melanoma cells and enhances their metastatic ability." (PMID 37686660, 2023). "Previous research revealed that loss‐of‐function mutations in FBXW7 in melanoma tumours confer resistance to anti‐PD1 therapies, which are currently frontline treatment in ccRCC." (PMID 35231161, 2022). "A recent study utilized an exome sequencing screen to characterize the functional impact of FBXW7 mutations in melanoma, and highlight its substrate NOTCH1 as a suitable therapeutic marker in the clinical setting." (PMID 33822486, 2021). "FBXW7 as a critical tumor suppressor that is reportedly mutated and inactivated in melanoma, resulting in constitutive NOTCH1 activation." (PMID 33822486, 2021). "Based on these findings, it can be said that FBXW7 mutational inactivation represents a potent mechanism for constitutive NOTCH1 activation in melanoma." (PMID 33822486, 2021). "A recent study provided evidence of the recurrent mutations of the FBXW7 gene in human melanomas; in this context, it is important to point out that NOTCH1 is a substrate of this gene." (PMID 29156643, 2017). "Notch1, one of the most canonical substrates of FBXW7 69, was remarkably accumulated in cells upon the loss of FBXW7, and then promoted tumor growth and angiogenesis of melanoma." (PMID 28544818, 2017). "Aside from BAP1, the genetic mutation of another ubiquitin ligase FBXW7 has also contributed to the tumorigenesis of melanoma." (PMID 28544818, 2017). "Low expression of FBXW7 is significantly associated with poor prognosis in melanoma patients." (PMID 39213172, 2024). "Our previous study shows that FBXW7 mutations in macrophages may alleviate lung metastasis of murine melanoma, but the detailed mechanisms underlying these results remain unknown." (PMID 33260160, 2020). "Reports have suggested that FBXW7 expression is remarkably lower in primary melanoma than in dysplastic nevi and further lowered in the metastatic state compared to primary melanoma and its reduced expression is associated with poor 5-year survival of melanoma patients." (PMID 30791487, 2019). "And therefore, FBXW7 mutations may be considered as a “driver” genetic event in malignant melanoma." (PMID 33822486, 2021). "The expression of FBXW7 was shown to be lower in metastatic melanoma than in original melanoma and related to a poor 5-year survival rate." (PMID 39823500, 2025). "The expression level of FBXW7 decreases with the stage of melanoma and depends on the morphological type of tumour and tumour invasion." (PMID 39340537, 2024). "Compared to normal skin tissues, 4 key CRGs (ABCC2, CA14, LDHB, PSEN2) were significantly upregulated while 2 key CRGs (EGR3, FBXW7) were significantly downregulated in melanoma tissues." (PMID 39213172, 2024). "Among them, 4 key CRGs (ABCC2, CA14, LDHB, PSEN2) were significantly upregulated and 2 key CRGs (EGR3, FBXW7) were significantly downregulated in melanoma tissues." (PMID 39213172, 2024). "By machine learning algorithms, we identified 6 key CRGs (ABCC2, CA14, EGR3, FBXW7, LDHB, and PSEN2) closely associated with melanoma." (PMID 39213172, 2024).
melanoma (continued). "The results indicated that high expression of PROM2, EGFR, AURKA, and low expression of IFNG, ARNTL, FBXW7 correlated with a poor prognosis of melanoma patients." (PMID 35692844, 2022). "FBXW7 has been found to be mostly inactivated in melanoma that results in constitutive NOTCH1 activation." (PMID 33822486, 2021). "Mutations in FBXW7, a tumor suppressor that regulates ubiquitin-mediated protein degradation, have been associated with resistance to anti-PD1 in melanoma by reducing MHC class I expression." (PMID 33106165, 2020). "Further, in vitro studies have revealed that FBXW7-inhibited melanoma cell migration via the mitogen-activated protein kinase/extracellular signal-regulated kinase (MAPK/ERK) signaling pathway." (PMID 30791487, 2019). "It was shown that downregulation of FBXW7 in melanoma leads to increased MITF-mediated dysregulation of oxidative phosphorylation and increased SOX10 mediated migration of melanoma cells." (PMID 31416288, 2019). "Mutations of several ubiquitination‐associated enzymes, such as BAP1, FBXW7 and PARK2, can lead to melanoma tumorigenesis." (PMID 28544818, 2017). "In fact, the reduced FBXW7 expression observed in some melanomas stabilizes the heat-shock factor 1, inducing a cell response and stimulating the metastatic potential of melanoma cells." (PMID 29156643, 2017). "Recent studies in various animal models have additionally supported a role for reduced FBXW7 expression in melanoma tumorigenesis." (PMID 29156643, 2017). "A recent study reported that Fbxw7 inhibited melanoma cell migration and served as a prognostic marker." (PMID 24884509, 2014). "FBXW7 is a critical tumor suppressor and one of the most deregulated ubiquitin-proteasome system proteins in human cancer, but its role in melanoma remains (largely) unknown." (PMID 35692844, 2022). "FBXW7 expression was detected downregulated, which is correlated with elevated expression of mitochondrial functional genes as well as poor prognosis of melanoma patients, dependent on its downstream MITF/PGC-1α pathway satisfying the metabolic needs of tumor cells." (PMID 35515121, 2022). "Thus, ablation of FBXW7 in melanoma cells leads to increased cell migration and stress fiber formation." (PMID 30791487, 2019). "In vitro silencing of FBXW7 in melanoma considerably enhanced MITF/PGC-1 signaling contributing to the augmentation of mitochondrial transcription program and may result in poor outcomes for the patients." (PMID 30791487, 2019). "Furthermore, knockdown of FBXW7 showed minimal impact on melanoma cell proliferation, but markedly potentiated the migratory capacity." (PMID 28544818, 2017). "In melanoma cells Fbxw7 abundance is decreased, resulting in increased HSF1 protein levels." (PMID 28194040, 2017). "FBXW7, as the ferroptosis driver, might be the potential mechanism in melanoma progression." (PMID 35692844, 2022). "Moreover, FBXW7 was also found to regulate the oncogene MITF in melanoma." (PMID 30791487, 2019). "The genes of HAMP, SLC7A5, CYBB, and IFNG were highly expressed in melanoma cell lines, while JDP2, TUBE1, PROM2, GPX2, FBXW7, and ARNTL were lowly expressed in melanoma cell lines." (PMID 35373463, 2022). "Although melanoma cells are highly resistant to MAPK inhibitors, a combination with MDM2 inhibitor, Nutlin-3A, resulted in elevated FBXW7 expression, p63 degradation, and apoptosis of melanoma cells effectively reversing MAPK inhibitor resistance." (PMID 35346215, 2022). "Finally, by comparing the feature genes identified by the three machine learning approaches, six common key CRGs were identified as melanoma-related key CRGs, including ABCC2, CA14, EGR3, FBXW7, LDHB, and PSEN2." (PMID 39213172, 2024). "For example, mitogen-activated protein kinase/extracellular signal–regulated kinase (MAPK/ERK) pathway appears to be involved in melanoma tumorigenesis, for the treatment of MAPK/ERK kinase (MEK) inhibitors significantly reverses FBXW7 knockdown-induced cell migration." (PMID 35515121, 2022).
melanoma (continued). "In addition to FBXW7 self-ubiquitination, studies have shown that in melanoma cells the nuclear accumulation of MDM2 leads to MDM2-dependent ubiquitination and rapid downregulation of FBXW7 resulting in upregulation of FBXW7-degraded oncoproteins such as p63." (PMID 35346215, 2022). "Consequently, in MAPKi-resistant melanoma cells, nuclear enrichment of MDM2 most probably resulted in downregulation of FBXW7 and subsequent upregulation of p63." (PMID 36613518, 2022). "Altogether, given the abundance of SNCA in metastatic melanomas and possibly in other tumors, these findings indicate that SNCA may be a key regulator of metastasis through the FBXW7/NOTCH axis." (PMID 33822486, 2021). "Additionally, the present study found NOTCH1, c‐Myc, and Cyclin E to be consistently regulated by FBXW7 in melanoma as opposed to Aurora A (inconsistent) and myeloid cell leukemia sequence‐1 (MCL1) (unregulated)." (PMID 33822486, 2021). "Moreover, the nuclear staining of FBXW7 was in a strong negative correlation with patients' outcome, and forward multivariate Cox regression analysis revealed that nuclear FBXW7 expression was an independent factor for predicting melanoma prognosis." (PMID 28544818, 2017).